ZCCHC10 (zinc finger CCHC-type containing 10)
Synonyms: FLJ20094
Tractability: PROTAC: its protein half-life has been measured.
Gene: Protein-coding gene on chromosome 5 (132,996,985 to 133,026,604, reverse strand). Ensembl gene ENSG00000155329.
Subcellular location (Human Protein Atlas): Nucleoli rim; Nucleoplasm
Gene Ontology:
Molecular function: protein binding; nucleic acid binding; zinc ion binding
Genetic constraint (gnomAD): Loss-of-function variants: 12 observed, 18.88 expected, observed/expected ratio (o/e) 0.64, 90% interval 0.41 to 1.03. The upper end of that interval is the gene's LOEUF score, 1.03, which puts it in group 4 of 6, group 1 being the genes least tolerant of losing a copy. Missense variants: 173 observed, 195.82 expected, observed/expected ratio (o/e) 0.88, 90% interval 0.78 to 1. Synonymous variants: 59 observed, 69.06 expected, observed/expected ratio (o/e) 0.85, 90% interval 0.69 to 1.06.
Homologues: Orthologues: chimpanzee ZCCHC10 (100% identical), macaque ZCCHC10 (100% identical), dog ZCCHC10 (86% identical), pig ZCCHC10 (84% identical), mouse Zcchc10 (77% identical), guinea pig ZCCHC10 (77% identical), rat AABR07072108.1 (72% identical), zebrafish zcchc10 (55% identical), Drosophila melanogaster CG5516 (35% identical).
Diseases named in the same sentence as ZCCHC10 in open-access papers:
ZCCHC10 is named in the same sentence as 8 diseases in open-access papers, as found by Europe PMC text mining. Sharing a sentence is not in itself a finding about the gene and the disease. The quoted sentences say what the papers report.
lung carcinoma (3 papers, 2019 to 2022). "These shreds of evidence underline that ZCCHC10 plays its role as a tumor suppressor gene in CRC and lung cancer." (PMID 35794979, 2022). "Functional studies showed that ZCCHC10 dramatically suppressed lung cancer cell proliferation, colony formation, migration, invasion, and cisplatin resistance in vitro, as well as tumor growth and metastasis in vivo." (PMID 31138778, 2019). "To explore the roles of ZCCHC10 in lung cancer, we used the lentivirus-mediated expression system to stably over-express ZCCHC10 in A549 and H460 cell lines, which lack endogenous ZCCHC10." (PMID 31138778, 2019). "We have demonstrated that ZCCHC10 suppressed invasion and metastasis of lung cancer, whereas epithelial-mesenchymal transition (EMT) is a vital process in the invasion and metastasis of cancers." (PMID 31138778, 2019). "Based on these results, ZCCHC10 expression is a prognostic marker for lung cancer, particularly LUAD." (PMID 31138778, 2019). "Moreover, ZCCHC10 expression has a greater benefit for non-smokers than smokers among patients with lung cancer." (PMID 31138778, 2019).
melanoma (2 papers, 2019 to 2022). A malignant, usually aggressive tumor composed of atypical, neoplastic melanocytes. "Recently, it was reported that interaction of PITX1 and ZCCHC10 contributes to TERT regulation in melanoma cells, and it was shown that PITX1 binds to the TERT promoter in gastric cancer cells." (PMID 35267575, 2022). "Among these, ZCCHC10 showed lower expression in melanoma tissue samples when compared with normal melanocyte cells." (PMID 31404068, 2019). "We next performed western blotting analysis to investigate the expression profiles of ZCCHC10 in human melanoma cell lines." (PMID 31404068, 2019). "To further explore the relationship between ZCCHC10 and hTERT gene, we performed qRT-PCR analysis to determine hTERT mRNA expression level in melanoma cell lines." (PMID 31404068, 2019). "The expression levels of ZCCHC10 proteins were significantly reduced in all six melanoma cell lines (A2058, SKMEKL28, G361, HMV1, CRL1597 and GAK) when compared to normal human epidermal melanocyte cells." (PMID 31404068, 2019). "Furthermore, qRT-PCR analysis indicated that ZCCHC10 mRNA expression was markedly decreased in 11 out of 12 human clinical melanoma specimens when compared with normal melanocyte cells." (PMID 31404068, 2019). "Moreover, expression levels of ZCCHC10 in human melanoma cells were significantly lower when compared with normal melanocyte cells." (PMID 31404068, 2019). "In addition, overexpression of both the PITX1 and ZCCHC10 genes showed significant suppression of hTERT transcription when compared to that of each gene in melanoma cell lines." (PMID 31404068, 2019). "In addition, ZCCHC10 expression levels showed marked decrease in the majority of melanoma cell lines and tissues." (PMID 31404068, 2019). "Interestingly, ZCCHC10 protein levels negatively correlated with hTERT mRNA levels in melanoma cell lines." (PMID 31404068, 2019). "Co-expression of PITX1 and ZCCHC10 resulted in inhibition of hTERT transcription, in melanoma cell lines, whereas mutate-deletion of homeodomain in PITX1 that interact with ZCCHC10 did not induce similar phenotypes." (PMID 31404068, 2019).
acute myeloid leukemia (1 paper, 2025). Acute myeloid leukemia (AML) is a group of neoplasms arising from precursor cells committed to the myeloid cell-line differentiation. "ZCCHC10 (zinc finger CCHC-type containing 10) has been shown to play a tumor suppressive role in acute myeloid leukemia (AML), but the underlying mechanism is not clear." (PMID 41143260, 2025).
lung adenocarcinoma (1 paper, 2019). A carcinoma that arises from the lung and is characterized by the presence of malignant glandular epithelial cells. "In this paper, we demonstrate that ZCCHC10 expression levels are statistically lower in lung adenocarcinoma tissues than the corresponding adjacent noncancerous tissues, and decreased expression of ZCCHC10 mRNA predicts poorer survival of the patients." (PMID 31138778, 2019).
tumor (3 papers, 2019 to 2025). "Our previous study has shown that ZCCHC10 (zinc finger CCHC-type containing 10) plays a tumor suppressive role in AML." (PMID 41143260, 2025). "To confirm the tumor-suppressive function of ZCCHC10 in vivo, we generated subcutaneous xenograft models." (PMID 31138778, 2019).
cancer (2 papers, 2019). A tumor composed of atypical neoplastic, often pleomorphic cells that invade other tissues. "Through analyzing cancer microarray database on the Oncomine platform, we found that the levels of ZCCHC10 mRNA in LCC, LUAD, and LUSC tissues were significantly lower than lung normal tissues (foldchange: −1.520, −1.334, and −1.19, respectively)." (PMID 31138778, 2019).
ZCCHC10 also shares sentences with these, for which no sentence is quoted: gastric cancer (1 paper); lymph node metastasis (1).